BRAF (B-Raf proto-oncogene, serine/threonine kinase)
Diseases named in the same sentence as BRAF in open-access papers (continued):
Sharing a sentence is not in itself a finding about the gene and the disease.
metastatic disease (continued). "In the new multiple regression analyses, factors associated with improved ETS that were consistent in both the PRIME and PEAK studies were panitumumab treatment, liver-only metastatic disease and WT BRAF status." (PMID 29080924, 2018). "The concordance rate between primary and metastatic tumors for BRAF and PI3CA status is also high, ranging from 97 to 100% for BRAF and 93 to 95% for PI3CA." (PMID 30234115, 2018). "In a new exploratory analysis assessing factors associated with DpR, the only factors that were consistently associated with improved DpR across the PRIME and PEAK studies were panitumumab treatment, liver-only metastatic disease and WT BRAF status." (PMID 29080924, 2018). "The results showed that no statistical differences in the frequencies of EGFR, KRAS, HER2, BRAF, and PIK3CA mutations and other GMs were observed between unpaired primary and metastatic tumors." (PMID 29518290, 2018). "In contrast, NRAS-mutant patients were more likely to develop early nodal relapse and metastatic disease than the BRAF-mutant or WT cohort suggesting that they were at highest risk for disease progression and ultimately disease-specific mortality." (PMID 28797232, 2017). "Comparative genomic analyses have identified a high level of concordance particularly for RAS, BRAF, and PIK3CA mutations between colorectal primary and metastatic tumors." (PMID 28178681, 2017). "The selective inhibitors of mutant BRAF kinase have become the key component of the treatment of metastatic disease." (PMID 27042173, 2016). "In patients with metastatic disease, several options are now available (namely ipilimumab, nivolumab, pembrolizumab, cytotoxics, interleukin-2, anti-MEK, and anti-BRAF agents in BRAF mutated MM), and so long-term survivors are a realistic possibility." (PMID 27368007, 2016). "Although the presence of the mutation is not independently predictive of poor outcome, a significant percent of BRAF-positive patients will develop recurrence and metastatic disease." (PMID 25712893, 2015). "For example, the discordance of KRAS and BRAF mutations due to genetic diversification of metastatic cells compared to their primary tumor, may explain the lack of efficacy and the emergence of subsequent resistance when treating metastatic disease with EGFR monoclonal antibodies." (PMID 25902072, 2015). "More specifically, somatic mutations in the BRAF, NRAS, KIT, and GNAQ genes are critical to correctly stage and manage patients with metastatic disease who can nowadays benefit from these modern molecular targeted therapies." (PMID 24591764, 2014). "Inhibitors of the BRAF/MEK/ERK signaling cascade have been proven highly effective in the metastatic disease although displaying different side effects." (PMID 25526431, 2014). "We analyzed PFS on conventional treatment (before referral to phase 1 clinic) for metastatic disease according to BRAF status." (PMID 22039425, 2011). "It is possible that the BRAF status of metastatic tumour is different compared with that of primary tumour." (PMID 19861964, 2009). "In Patient 8, the BRAF p.V600K mutation was present in both the primary and metastatic tumors, but absent in the nevus, indicating that the nevus is not clonally related to either." (PMID 39912776, 2025). "Additionally, 348 (68.5 %) received bevacizumab, 148 (29.1 %) received anti-EGFR therapy, 115 (22.6 %) received Trifluridine/Tipiracil (Lonsurf), and 12 (2.4 %) received BRAF inhibition during their treatment for metastatic disease." (PMID 40184716, 2025).
metastatic disease (continued). "The univariate Cox regression analysis revealed that the number of metastatic tumors, cN stage, KRAS and BRAF gene mutations, patient age, primary tumor site, CEA levels, neutrophil count, platelet count, and D-Dimer levels exhibited a significance level of P <0.1." (PMID 39991568, 2025). "In predicting DFS, factors such as the number of metastatic tumors, cN stage, KRAS and BRAF mutations, patient age, primary tumor site, CEA levels, neutrophil count, monocyte count, platelet count, and D-Dimer levels were identified as significant predictors for DFS using univariate analysis." (PMID 39991568, 2025). "Concomitant RNF43 mutation in metastatic disease, was associated with a significantly higher incidence of disease control from combined BRAF and EGFR inhibition, when compared to those without an RNF43 mutation (100% vs. 54%, p = 0.02)." (PMID 41002577, 2025). "TERT promoter mutations were also enriched in Class 2 but not in Class 3 BRAF mutant metastatic tumors." (PMID 38275886, 2024). "For patients with BRAF mutations, BRAF inhibitors have shown some success in both primary and metastatic tumors in one study, although the metastatic tumors in this study were not specific to bone or the spine." (PMID 39335124, 2024). "Computed tomography (CT) of the chest, abdomen, and pelvis showed no metastatic disease, and molecular profiling was negative including absent BRAF mutation." (PMID 39262554, 2024). "Nowadays, CRC patients without metastases are not screened for BRAF mutations, and further molecular examination is only conducted in metastatic disease." (PMID 36672497, 2023). "Furthermore, we found that CM presents a significant concordance in BRAF status between primary and metastatic tumors than in previous meta-analyses, probably due to technical advances, although a minority of patients showed inconsistencies." (PMID 38003476, 2023). "In contrast, the BRAF mutation has not been associated with the most invasive and metastatic disease in children with PTC; therefore, more data are needed to understand the natural history of BRAF-driven PTC in this population." (PMID 36765847, 2023). "Therefore, subpopulations with adverse prognostic factors for metastatic disease (including BRAF V600E mut, older age, higher tumour burden, poor performance status) are likely to be underrepresented." (PMID 37240418, 2023). "BRAF mutations are a negative prognostic marker, with worse survival outcomes being reported in a metastatic disease." (PMID 39132649, 2023). "Although data on BRAF mutational status were available in most of the primary or metastatic tumors, not all cases had this information." (PMID 38202181, 2023). "Interestingly, BRAF scores in metastatic tumor samples appear to be overall lower than BRAF scores in primary tumor samples even though there is higher BRAF expression in metastatic mutant samples." (PMID 35044091, 2022). "In metastatic disease, BRAF V600E-mt confers resistance to EGFR inhibitor therapy." (PMID 35323316, 2022). "Furthermore, considering the low concordance in BRAF mutation status between primary and metastatic tumors, we further analyzed the correlation between LDHA expression and BRAF status of COAD patients." (PMID 34307169, 2021). "Within the metastatic disease setting, the presence of KRAS/NRAS mutations provides resistance to cetuximab and panitumumab, while BRAFV600E mutation predicts response to anti-EGFR targeted therapies in combination with a BRAF inhibitor." (PMID 34201502, 2021). "This was observed also in the present study; BRAF mutations were not only associated with metastatic tumors, but also found to be a negative prognostic marker for OS in a subgroup analysis with advanced CRCs." (PMID 33854094, 2021). "Although BRAF V600E mutations portend a dismal prognosis, exceptions to this general rule do exist, therefore exclusion from resection of metastatic disease should not be solely based on the presence of BRAF mutations." (PMID 31661924, 2019).
metastatic disease (continued). "Other factors to consider in terms of prognosis and prediction of response to treatment include the sidedness of the cancer (right vs left), RAS and BRAF status, which affect prognosis in metastatic disease, and microsatellite instability status, which affects the outcome of adjuvant treatment." (PMID 29611518, 2018). "Neither primary nor metastatic tumor harbored KRAS/BRAF mutations according to polymerase chain reaction using formalin-fixed paraffin-embedded tissues." (PMID 29960592, 2018). "Factors associated with improved DpR in the final multiple regression model were panitumumab treatment (vs. bevacizumab), liver-only metastatic disease (vs. liver + other or other only metastases), WT BRAF status (vs. mutant) and age (decreased vs. increased, continuous variable)." (PMID 29080924, 2018). "Factors associated with improved DpR in the final multiple regression model were panitumumab treatment (vs. FOLFOX4 alone), liver-only metastatic disease (vs. liver + other or other only), WT BRAF status (vs. mutant) and an ECOG performance status of 0 or 1 (vs. 2)." (PMID 29080924, 2018). "Considering the time to progression as metastatic disease (from the detection of primary CRC to the diagnosis of first distant metastasis, TTPM), the occurrence of BRAF mutations again remained a statistically-independent negative prognostic factor [p = 0.009; HR: 2.97; 95 % CI: 1.26–6.33]." (PMID 27737711, 2016). "On the other hand, no conclusions can be made for issues related to differences among primary and metastatic tumours, and whether they may represent an intrinsic mechanism of resistance to BRAF codon 600 TKIs." (PMID 26690267, 2015). "Ultimately our results from a large dataset of patients with metastatic disease do not support loss of PTEN expression based on CNA as a prognostic marker in the overall population or any subgroups based on KRAS or BRAF mutation status." (PMID 23930204, 2013). "The potential presence of heterogeneity among metastatic tumors suggest that relying on a single biopsy specimen for treatment decisions with BRAF inhibitors could exclude some patients who would benefit from the therapy." (PMID 22235286, 2012). "Therefore, all metastatic tumours, except the left S6 tumour, were considered to be without a BRAF V600E mutation." (PMID 39139611, 2024). "It is crucial to consider that most analyses assessed by clinical trials and observational studies belong to an era when the potential for immunotherapy has not been yet available for patients with recurrent metastatic tumors, especially those with BRAF-mutated MSI." (PMID 38786299, 2024). "In addition to the kinase group enrichment, for each set of results (i.e., all samples, high purity, BRAF mutants, etc.)we looked for BP enrichment among significant genes, as a hypothesis-free approach to further characterize the metastatic tumors." (PMID 35560144, 2022). "In this subgroup, BRAF V600E/K mutation was comparable in cMKP and MUP patients (46.6% vs. 51.0%, P = 0.114), whereas patients with MUP more frequently presented with advanced and metastatic disease at primary diagnosis with worse ECOG performance status, higher LDH, and CNS metastases." (PMID 33774697, 2021). "Importantly, this observation was again confirmed in the metastatic tumors of TCGA (n = 287), with the T cell score showing a similar distribution in BRAF-mutated, NRAS-mutated, and double-WTs but showing no prognostic effect in NRAS-mutated tumors." (PMID 29664013, 2018). "Low-level tumor LINE-1 methylation was associated with higher pN stage and metastatic disease, and inversely associated with poor tumor differentiation, MSI-high, MLH1 hypermethylation, CIMP-high, and BRAF mutation (P ≤ 0.003 with the adjusted α level of 0.003 for multiple hypothesis testing)." (PMID 27391152, 2016).
metastatic disease (continued). "Within the BRAF(+) group 7 cancer recurrences were noted (5.5%), including 6 local relapses and 1 distant metastases, whereas in the BRAF(-) group 5 cancer recurrences (4.7%) were reported, including 3 local relapses and 2 cases of local relapse with concurrent metastatic disease." (PMID 26177218, 2015). "These patients essentially have a “false negative” biopsy result, as different, non-biopsied metastatic tumor sites may harbor a BRAF mutation." (PMID 22235286, 2012). "Nine prognostic factors were then identified: metastatic tumor count, cN stage, KRAS and BRAF status, patient age, primary tumor location, neutrophil and platelet counts, and D-Dimer level." (PMID 39991568, 2025). "Despite advances in targeted therapies (e.g., BRAF/MEK inhibitors) and immunotherapies (e.g., anti-PD-1/PD-L1/CTLA-4), clinical outcomes remain variable, particularly in metastatic disease, where 5-year survival rates drop below 30%." (PMID 40821828, 2025). "In metastatic disease, treatment is based on the genetic profile of the tumor (RAS, BRAF, HER2, or MSI/dMMR) and the extent of the disease." (PMID 40723882, 2025). "For locally advanced or metastatic disease, systemic therapies including chemotherapy, immunotherapy, and targeted inhibitors of the MAPK and BRAF pathways are employed." (PMID 40361310, 2025). "Although she was feeling improved, restaging scans obtained 5 months into BRAF/MEK therapy showed a progression in peritoneal, splenic, pelvic, and uterine implants but a decrease in metastatic disease in the liver and psoas." (PMID 39234402, 2024). "CDKN2A and CKDN2B deletions and BRAF and TERT amplifications were common in the metastatic tumors of SUM and AM." (PMID 37686691, 2023). "Immune-checkpoint inhibitors first became available for metastatic disease in 2017 and for patients with stage III disease in 2019, while BRAF inhibitors first became available for systemic disease in 2015 and for patients with stage III disease in 2020." (PMID 37892990, 2023). "They found nine patients with different BRAF, NRAS, or TERT genotypic profiles between their metastatic tumors." (PMID 35887633, 2022). "BRAF and MMR gene alterations were more frequent in the primary tumor tissues than the metastatic tumor tissues." (PMID 35592200, 2022). "In this report, we performed a retrospective analysis on 52 consecutive patients who were homogeneously treated with BRAF and MEK inhibitors, as current standard treatment in BRAF mutant metastatic disease." (PMID 30939167, 2019). "The determination of KRAS, BRAF, and MSI status has become an indispensable step in therapeutic planning, especially in patients with metastatic disease." (PMID 31828035, 2019). "Increased infiltration of metastatic tumors with both CD4 and CD8 cells in one study, and of CD8 cells, but not CD4 cells in another study was observed after treatment with BRAF inhibition." (PMID 24194739, 2013). "The majority of targeted compounds, for example, EGFR, BRAF and MET inhibitors, as well as molecules directed towards rearranged kinases, are particularly effective when administered in the very beginning of the treatment of metastatic disease." (PMID 38966170, 2024). "The literature data consistently show a negative prognostic impact of KRAS and BRAF mutations in MSI patients on long-term outcomes such as RFS and OS, emphasizing the adverse effects of these mutations in metastatic disease rather than in operable cases." (PMID 38786299, 2024). "A proportion of 80% (4/5) of the patients whose lesion tested positive for BRAF V600E received anti-BRAF therapy in our cohort (one patient did not have systemic metastatic disease and did not receive any systemic chemotherapy)." (PMID 38136349, 2023). "The MAPK pathway showed mutations in the BRAF, KRAS, and MAP2K1 genes in three brain metastatic tumors that were not present in their breast primary tumors." (PMID 36507516, 2022).
metastatic disease (continued). "A BRAF V600E mutation was detected in NGS tissue analysis but not in liquid biopsy in a case (patient E) with low tumor burden and lung limited metastatic disease." (PMID 31597339, 2019). "BRAF exon 15 and NRAS exon 1 and 2 were investigated by Sanger sequencing of formalin fixed paraffin embedded (FFPE) primary tumors from time of diagnosis, and metastatic tumors collected before inclusion in the clinical trial." (PMID 31767937, 2019). "One limitation of this study is that it does not cover metastatic disease and therefore further analysis of this combined score in BRAF mutant metastatic patients is also warranted." (PMID 29988110, 2018). "Of 30 metastatic tumors enrolled in our study, 20 % included follicular and diffuse sclerosing variants of PTC and FTCs, which were all negative for the BRAF V600E mutation." (PMID 26857243, 2016). "In primary tumors lacking KRAS, NRAS, or BRAF mutations, we did identify occult alterations in the EGFR/RAS pathway that in some patients were private to the metastatic tumor." (PMID 25164765, 2014). "Interestingly, melanoma antigen expression in metastatic tumors was decreased at the time of tumor progression in patients treated with a BRAF inhibitor and partially restored upon initiation of dual MEK and BRAF blockade." (PMID 24194739, 2013). "The metastatic disease treatment targeting EGFR is found to be efficient only if KRAS and BRAF are not mutated." (PMID 21103049, 2010). "While BRAF mutations may not currently influence prognosis, they could become significant as BRAF/MEK inhibitors may be used to treat metastatic disease, similar to their application in CM." (PMID 40831998, 2025). "Unfortunately, a formal comparison between primary and metastatic tumors in response to BRAF inhibitors could not be performed since we did not have access to the primary tumor." (PMID 39018564, 2024). "The patient exhibited a rapid disease response to ALK tyrosine kinase inhibitors alectinib with a complete remission of widespread metastatic disease and progression-free survival of more than 26 months, but not to darafenib plus trametinib targeted BRAF V600E therapy." (PMID 36221356, 2022). "Among patients treated for metastatic disease, in the univariate analysis, OSICI was not affected by factors such as age, sex, race, pre-treatment lactate dehydrogenase level, or BRAF status; thus, no multivariate analysis was conducted." (PMID 40723182, 2025). "Similarly, our study found that the frequencies of EGFR, KRAS, HER2, BRAF, and PIK3CA mutations in TKI‐naive samples and the frequencies of sensitizing EGFR and T790M mutations in TKI‐relapsed samples showed no statistical differences between unpaired primary and metastatic tumors." (PMID 29518290, 2018).